FLG (filaggrin)
Diseases named in the same sentence as FLG in open-access papers (continued):
Sharing a sentence is not in itself a finding about the gene and the disease.
food allergy (31 papers, 2015 to 2026). Gastrointestinal disturbances, skin eruptions, or shock due to allergic reactions to allergens in food. "There are several studies implicating that mutation of the filaggrin gene results in the development of food allergies, such as peanut allergy." (PMID 40077585, 2025). "Filaggrin loss-of-function mutations are associated with the development of food allergy in older children through eczema, as well as food allergy sensitization during early childhood." (PMID 41016999, 2025). "A potential genetic link between food allergy and AD is demonstrated by filaggrin gene mutations and the increased risk of peanut allergy in a double-blind placebo-controlled food challenge." (PMID 39000023, 2024). "The greater likelihood of food allergy in people with mutations in filaggrin, a protein involved in maintaining the skin barrier, favoured the concept (OR: 31 [95% CI: 3 to >100)." (PMID 36506645, 2022). "Considering the wide spectrum of phenotypes possibly associated to FLG mutations, this study aimed to identify the association of FLG loss-of-function variants with allergic phenotypes, in particular with severe food allergy." (PMID 33440636, 2021). "Genetic variants in filaggrin (FLG) have been suggested to be associated with the increased risk of food allergy, with an association with peanut allergy specifically." (PMID 34833150, 2021). "More importantly, this study confirmed the role of skin barrier dysfunction and food allergy, while our study, beyond confirming association with FA identified in previous studies, shows as a new finding the correlation of FLG mutations with disease severity." (PMID 33440636, 2021). "FLG-LOF mutations were associated with food allergy and food allergen sensitization as determined by an allergen panel including egg, milk, soya, wheat, cod, and peanut." (PMID 32536107, 2020). "In the population-based study of pediatric food allergy, eczema and filaggrin gene loss-of-function mutations, which are associated with reduced skin barrier integrity, are identified as the risk factors for food sensitization." (PMID 27853507, 2016). "Recently, it was shown that loss-of-function mutations of filaggrin (FLG) are a major risk factor for peanut food allergy." (PMID 26941931, 2015). "In the Isle of Wight cohort, filaggrin loss-of-function mutations were associated with food sensitization in the early years and food allergy later in childhood, suggesting that skin barrier function per se is important in the development and persistence of food allergy." (PMID 35887996, 2022). "While our results confirmed the role of FLG null mutations in food allergy, a residual association was still detectable between FLG and the repetin gene (RPTN), which could point to additional genetic risk factors in this region." (PMID 29051540, 2017). "In fact, FLG loss of function has been directly associated with human food allergy." (PMID 27417371, 2015). "In pediatric patients with AD, KRT5, KRT14, KRT16, FLG breakdown products, and AD clinical severity were predictive of concomitant food allergy." (PMID 40141720, 2025). "Genetic association studies have identified some risk alleles for food allergies, particularly in the genes MALT1, FLG, and HLA; these findings implicate genes involved in immune and barrier function in the development of food allergies." (PMID 36501184, 2022). "Also, genetic mutations affecting skin barrier proteins, such as FLG and serine protease inhibitor Kazal type 5 (SPINK5), can significantly impair the skin’s protective function, leading to food allergies." (PMID 40290033, 2025). "In a Denmark population (n = 7931, age: 18–69), filaggrin gene loss-of-function mutation was associated with self-reported food allergy, including wheat allergy, but not oral allergy syndrome (OR for wheat allergy 3.59; 95% CI 1.61–8.02)." (PMID 40077585, 2025).
food allergy (continued). "We also review current knowledge of topical intervention to improve skin barrier function as a strategy for prevention of food allergy, including moisturizer therapy and new topical therapy targeting upregulation of skin barrier-related molecules, such as filaggrin (FLG)." (PMID 36904070, 2023). "In food allergy, the impaired skin barrier resulting from defects in filaggrin expression has been hypothesized as a gateway for food allergens and as a way to avoid the oral tolerance pathways of the gut mucosa." (PMID 27417371, 2015). "There is no filaggrin in the intestinal mucosa, but studies described a change in the tight junctions due to higher TNF‐α concentration present in patients with food allergies." (PMID 40386328, 2025).
ichthyosis (31 papers, 2009 to 2025). Disorders of cornification that are characterized by visible scaling and/or hyperkeratosis of most or all of the skin. "Immunohistochemically, a deficiency of filaggrin can be quantified, which correlates with the number of mutations (one or two mutations in the filaggrin gene) and thus, the severity of ichthyosis." (PMID 34066992, 2021). "Since filaggrin binds to and condenses the keratin cytoskeleton as a skin barrier, loss of filaggrin leads to a poorly formed stratum corneum (ichthyosis) and is also prone to water loss (xerosis)." (PMID 34200222, 2021). "Taken together, the present study of four Pakistani families supports previous research that biallelic mutations in TGM1, SULT2B1, SPINK5, and FLG cause human ichthyoses." (PMID 33807935, 2021). "IV, the most common hereditary form of ichthyosis, is linked to filaggrin (FLG) mutations, that lead to the stratum corneum (SC) disruption, thereby increasing skin permeability, transepidermal water loss (TEWL), and susceptibility to allergens and microorganisms." (PMID 41305004, 2025). "The loss of the late epidermal differentiation protein filaggrin plays a crucial role in skin barrier dysfunction in AD, leading to impaired formation of the impenetrable barrier known as the water loss (xerosis) and stratum corneum (ichthyosis)." (PMID 40429704, 2025). "Besides R311P, the K199E and P314T mutations were also found to abolish filaggrin proteolysis, contributing to the development of ichthyosis." (PMID 39098535, 2024). "We therefore speculate that our patient’s pyramidal decussation anomalies may be caused by the same FLG mutations that cause his ichthyosis." (PMID 32252685, 2020). "Thus, our results strongly suggest that genetic variants in ASPRV1 can cause ichthyosis by altering filaggrin processing." (PMID 28249031, 2017). "Interestingly, since nonsense mutations are the most frequent pathogenic variants of FLG and, although more rarely, of other ichthyosis-related genes, nonsense suppression therapy could be a promising approach also for the treatment of patients affected by hereditary skin diseases." (PMID 38791074, 2024). "Replacement of the highly conserved leucine residue at the P2 position of the cleavage site was supposed to result in aberrant filaggrin processing and consequently contribute to the development of ichthyosis." (PMID 39098535, 2024). "It is therefore necessary to analyze both steroid sulfatase (STS) and filaggrin (FLG) genes to exclude combined forms of ichthyosis." (PMID 37623486, 2023). "Indeed, filaggrin deficiency might promote a Th17 immune response that can be found not only in AD but also in other inflammatory skin diseases (e.g., psoriasis and ichthyoses)." (PMID 35628125, 2022). "Noteworthy, the Piga null mouse model develops the Harlequin ichthyosis phenotype due to impaired processing of filaggrin, a protein involved in epidermal cell permeability and homeostasis." (PMID 32635232, 2020). "Coexistence of TGM1 and FLG mutations in a newborn with congenital ichthyosis is not well described in the literature." (PMID 37736478, 2023). "We deem it unlikely that such an event would coincidentally affect a gene with a known role in filaggrin processing without being causative for the ichthyosis phenotype." (PMID 28249031, 2017). "A previous study suggested a strong association between filaggrin mutation of the Ichthyosis-related gene and the development of AE in IgE-allergic AE patients, while a tendency toward a lower incidence of ichthyosis in IgE-allergic AE compared to non-IgE-allergic AE was reported in another study." (PMID 26239460, 2015). "Patient ID-58 had been previously classified as vulgar ichthyosis on the basis of an orthokeratotic hyperkeratosis, absence of granular layer and reduced filaggrin staining." (PMID 26762237, 2016). "Consequently, the FLG gene is not always included in the panel of genes to be analyzed for the molecular diagnosis of the rarest forms of ichthyosis." (PMID 38791074, 2024).
ichthyosis (continued). "Interestingly, both neonatal Flgft/ft and DM mice have significant ichthyosis (P < .001) compared with WT mice, but Mattma/ma mice did not, indicating the postnatal importance of filaggrin (see Fig E5, A, and E6, A)." (PMID 24084074, 2013).
allergic rhinitis (18 papers, 2011 to 2025). Inflammation of the nasal mucous membranes caused by an IgE-mediated response to external allergens. "Maternal allergic history may reflect a heritable predisposition to atopy, with several studies identifying polymorphisms in immune-related genes such as IL-4, IL-13, and the filaggrin gene (FLG) that are linked to an increased risk of allergic rhinitis." (PMID 40422270, 2025). "Among the genes, mutations in the filaggrin gene (FLG) is the most profound single gene isolated that greatly increases the risk of contact allergy, allergic rhinitis, and peanut allergy." (PMID 33937097, 2021).
peanut allergy (18 papers, 2011 to 2025). "Loss-of-function mutations in the FLG gene, which encodes the key epidermal barrier protein filaggrin, are strongly associated with AD and peanut allergy." (PMID 41153664, 2025). "Genetic associates of peanut allergy such as the filaggrin (FLG) loss‐of‐function mutations have also been reported." (PMID 35108754, 2022). "As a defect in the skin barrier is proposed to be a risk factor of development of peanut allergy, attention is also paid to the filaggrin-filament binding protein in the stratum corneum of the skin." (PMID 34204606, 2021). "Other epidemiological and clinical studies reported the connection between FLG mutation and peanut allergy, while the hazelnut appeared for the first time in this study." (PMID 33440636, 2021). "A primary example of this are loss-of-function mutations in the filaggrin gene (Flg) that correlate with peanut allergy in humans." (PMID 33362786, 2020). "In particular, a link has been observed between FLG gene mutation and peanut allergy: the FLG deficiency allows food allergens to penetrate through the skin, interact with the immune system, and induce FA." (PMID 26936273, 2016). "If these children had been included, we would have expected a higher rate of FLG null mutations, given the known association between peanut allergy and FLG null mutations." (PMID 25457149, 2015). "Filaggrin (FLG) loss-of-function mutations lead to an impaired skin barrier associated with peanut allergy." (PMID 25282568, 2014). "Filaggrin mutations represent a significant risk factor for IgE-mediated peanut allergy, indicating a role for epithelial barrier dysfunction in the pathogenesis of this disease." (PMID 21377035, 2011). "In conclusion, FLG null mutations not only represent a highly significant genetic risk factor for AD but also are the single most significant genetic risk for peanut allergy that has been identified to date." (PMID 21377035, 2011). "Many studies have indicated that transcutaneous allergic sensitization may be facilitated by FLG null-mutations, and that both peanut allergy and AD are strongly associated with FLG loss-of-function variants, as well as other cutaneous conditions." (PMID 33440636, 2021). "Here we have shown that FLG mutations confer a risk for peanut allergy in the absence of clinical evidence of AD." (PMID 21377035, 2011).
xerosis (17 papers, 2002 to 2025). "Atopic dry skin is associated with a marked reduction of skin barrier proteins, such as filaggrin (FLG) and loricrin (LOR)." (PMID 28892018, 2017). "Loss of function mutations in the FLG gene are associated both with AD and xerosis (dry skin)." (PMID 38542749, 2024). "From a genetic point of view, patients may present with a predetermined defect of the skin barrier (e.g., filaggrin-FLG deficiency due to mutation of the FLG gene), which clinically manifests as dry skin (xerosis)." (PMID 36839897, 2023). "When tested in an acetone-induced dry skin mice model, ACTPER significantly ameliorated dry skin-induced itch via the upregulation of filaggrin expression." (PMID 31216667, 2019). "The onset of winter xerosis results in a transient but acute perturbation of filaggrin proteolysis and vitamin D analogs have been shown to increase filaggrin expression." (PMID 23112909, 2012). "Therefore, an effective treatment for dry skin that works by improving the expression of filaggrin could potentially be developed as a therapeutic agent for any antihistamine-resistant itch." (PMID 31216667, 2019). "Use of skin moisturizers to treat xerosis may indeed be higher in FLG-null carriers." (PMID 24380925, 2014). "In non-lesional AD, FLG null mutations leading to reduced filaggrin result in dry skin, whereas non-lesional AD skin from FLG wild-type patients does not exhibit xerosis." (PMID 35628125, 2022).
melanoma (15 papers, 2018 to 2025). A malignant, usually aggressive tumor composed of atypical, neoplastic melanocytes. "High filaggrin mRNA expression (FLG and/or FLG2 transcripts) is associated with a poor overall survival in melanoma, and a positive correlation was observed in the expression patterns between the FLG and FLG2 transcripts." (PMID 40765578, 2025). "Currently, Kezic S. has reported that FLG may serve as a potential biomarker for a reduced risk of melanoma, however, there are limited reports about the associations between FLG and melanoma." (PMID 33178610, 2020). "To gain insight into the underlying context, we classified the melanomas based on the filaggrin expression (filaggrinHigh/Low) and profiled the signaling context behind pruritic melanomas." (PMID 40765578, 2025). "Initial observations on the survival of melanoma patients stratified by filaggrin mRNA expression showed a significantly poorer survival in the filaggrinHigh group." (PMID 40765578, 2025). "The barrier molecule junctions plakoglobin, filaggrin, and dystonin play roles in melanoma growth and angiogenesis." (PMID 38255907, 2024). "Among these hub genes, we identified the attenuated expressions of CDH1, COL17A1, DSG1, KRT14, and FLG in melanoma metastases compared with primary melanoma via bioinformatics analysis upon the GSE8401 and TCGA datasets." (PMID 35054979, 2022). "Kaplan–Meier survival analyses showed that FLG, KRT5, DSG1, DSG3, and IVL expression levels were significantly associated with melanoma patient survival (p < 0.01)." (PMID 33178610, 2020). "Given that FLG, PKP1, and TGM1 are ECM related, their association with CTNND1 raises the possibility that altered adhesion dynamics converge with ECM remodeling to promote melanoma progression." (PMID 41321310, 2025). "Thus far, 8 out of 21 GLI targets we chose to validate—KRT16, S100A9, SOX9, BIRC7, EBI3, FLG, SAMMSON and SPRY2—were already implicated in melanoma pathogenesis." (PMID 36139698, 2022). "Filaggrin (FLG), was found to identify a distinct patient population with low immune cell infiltration in melanoma and ovarian cancer, and may protect cancer cells from immune cell infiltration and immune-mediated destruction." (PMID 33173439, 2020). "Thus, we can speculate that FLG may also play an important role in the melanoma progression as well as EGFR." (PMID 33178610, 2020). "Five key genes FLG, DSG1, DSG3, IVL, and EGFR were identified in the TCGA database and melanoma tissues." (PMID 33178610, 2020). "Therefore, based on the average of the combined FLG and FLG2 mRNA expressions, we classified the melanoma patients into the filaggrinHigh and filaggrinLow groups, respectively." (PMID 40765578, 2025). "We found LOR, EVPL, SPRR1A, FLG, DSP, and CSTA had been reported in previous studies on melanoma." (PMID 35003328, 2021). "The results suggested that FLG, DSG1, DSG3, IVL, and EGFR might play important roles and potentially be valuable in the prognosis and treatment of melanoma." (PMID 33178610, 2020). "Six targets—S100A9, FLG, SAMMSON, LY6D, CACNA2D2, and HES1—were found to have variable expression in different melanoma cell lines, so they could not be validated as GLI targets in melanoma." (PMID 36139698, 2022).
inflammatory skin disease (14 papers, 2010 to 2024). Inflammatory skin disorders covers a broad category that includes many conditions ranging in severity, from mild itching to grave medical health complications These disorders are common in people of all ages and races. "The effect of GATA3 expression change on FLG, which encodes the epidermal barrier protein filaggrin, in keratinocytes was pointed out in human inflammatory skin diseases." (PMID 39364404, 2024). "We focused on the relationship of PM2.5 and FLG, a critical component of the epidermal skin barrier, because it has been suggested that PM2.5 is strongly associated with the development of inflammatory skin diseases, and FLG is a key epidermal barrier protein in maintaining skin barrier function." (PMID 33497363, 2021). "Evidence for the involvement of microtubules was provided in a recent study in which treatment of reconstructed human epidermis with Th2 cytokines, as identified in inflammatory skin disorders, altered epidermal homeostasis and lowered the amount of filaggrin." (PMID 30923192, 2019). "Therefore, modulating the expression of filaggrin and adhesion molecules is a promising strategy to treat inflammatory skin disorders." (PMID 35002730, 2021). "Molecules related to skin barrier, such as filaggrin (FLG), involucrin (IVL), and loricrin (LOR), regulate skin permeability and prevent moisture evaporation, which prevents AD and various inflammatory skin disorders." (PMID 38314445, 2024).
rheumatoid arthritis (10 papers, 2008 to 2025). A chronic, systemic autoimmune disorder characterized by inflammation in the synovial membranes and articular surfaces. "TPO encodes a primary autoantigen in both Hashimoto's Thyroiditis (HT) and Graves' Disease (GD); PTPRN2, and FLG encode primary autoantigens in Type-1 Diabetes (T1D) and Rheumatoid Arthritis (RA) respectively." (PMID 24988487, 2014). "Regions of filaggrin molecules, which can act as immunoreactive epitopes reacting with antibodies in the sera of Rheumatoid arthritis patients, were found in a similar study." (PMID 34945953, 2021). "Our analysis revealed significantly higher IgG reactivity against the citrullinated fibrinogen β and filaggrin peptides as well as an IgA reactivity that was exclusive for citrullinated fibrinogen β peptide and C3 deposition in rheumatoid arthritis patients." (PMID 24797804, 2014). "More, PADs are though to be key factors in the pathophysiology of multiple sclerosis, Alzheimer's disease, and rheumatoid arthritis, and in the metabolism of the major epidermal barrier protein filaggrin." (PMID 18923650, 2008).